BRCA1 (BRCA1 DNA repair associated)
Diseases named in the same sentence as BRCA1 in open-access papers (continued):
Sharing a sentence is not in itself a finding about the gene and the disease.
ovarian carcinoma (continued). "Previous studies have mostly focused on high-risk populations, including patients with breast and ovarian cancer, or BRCA1/2 mutation carriers in Western countries." (PMID 35629239, 2022). "Women perceiving high risk of developing breast and ovarian cancer are more willing to undergo BRCA1/2 testing and prophylactic surgery." (PMID 35629239, 2022). "The estimated absolute risk of developing ovarian cancer by age 80 for BRCA1 carriers at the 99th PRS centiles were 63.2%, 66.3%, 59.0%, and 68.4% for the lasso, elastic net, stepwise and S4 models, respectively." (PMID 35027648, 2022). "BRCA1 ex9-12del is the most common variant in Mexican patients, and BRCA1 c.5095C > T is the most common variant in Arab breast and ovarian cancer patients." (PMID 35918668, 2022). "This study was performed to better understand rates and factors that influence patients in accepting a referral to genetics or testing for genes that predispose them to ovarian cancer (BRCA1/2)." (PMID 36547149, 2022). "About 10% of ovarian cancer patients were found to be associated with genetic risk and the first known susceptibility genes are BRCA1 and BRCA2." (PMID 36729997, 2022). "Pancreatic and prostate cancer were the first cancers after breast and ovarian cancer for which the efficacy of PARP inhibitors was evaluated in the presence of BRCA1/2 mutations." (PMID 35563100, 2022). "For epithelial ovarian cancer patients who received chemotherapy, we confirmed survival benefit for BRCA1 and BRCA2 germline pathogenic variant carriers." (PMID 36137114, 2022). "Several studies noted that the BRCA1 expression is negatively associated with progression-free survival and overall survival in epithelial ovarian cancer." (PMID 35280680, 2022). "People who inherit mutation in BRCA1 gene are at an increased risk of developing BC and ovarian cancer than the general population." (PMID 35300412, 2022). "Olaparib maintenance treatment provided significant PFS and OS benefits in patients with platinum-sensitive, relapsed ovarian cancer and a BRCA1/2 mutation." (PMID 35466318, 2022). "It had been estimated that the average cumulative risks by age 80 years in carriers of BRCA1 germline mutation were 72% and 44% for breast cancer and ovarian cancer, respectively." (PMID 36232807, 2022). "Hypermethylated BRCA1 was associated with high HRDsum and most abundant in ovarian cancer (16%) and testicular germ cell tumors (11%)." (PMID 35681079, 2022). "On contrary, the low-grade ovarian cancer is associated with BRCA1 and PALB2 mutations and presents worse survival among BRCA1 carriers." (PMID 35313928, 2022). "Currently, with the introduction of poly (ADP-ribose) polymerase (PARP) inhibitors, for BRCA1/2 mutated breast and ovarian cancer patients, the exact relationship between BRCA1/2 genes and sporadic TNBC/HGSC needs to be further investigated." (PMID 35986351, 2022). "Regardless the precise mechanism of action, however these findings modified the therapeutic armamentarium for BRCA1/2 deficient ovarian carcinoma over recent years." (PMID 35406579, 2022). "Pathogenic variants in BRCA1/2 are the most common cause of hereditary breast and ovarian cancer, underlying 5–10% of breast and 20% of ovarian cancers." (PMID 36344544, 2022). "With this algorithm of procedure, the sensitivity of detecting the BRCA1/2 gene mutation in ovarian cancer patients would increase to 77.8%, at a relatively low cost." (PMID 35382848, 2022). "The use of olaparib provides substantial benefits among women with newly diagnosed advanced ovarian cancer and a BRCA1/2 mutation." (PMID 35402276, 2022). "In each analysis, BRCA1/2 status was used as gene-level controls, and BRCA1/2 mutated-breast and ovarian cancer were used as the cancer type-level controls." (PMID 36497135, 2022). "BRCA1 was first described as a hereditary breast and ovarian cancer susceptibility gene in 1994, followed by BRCA2 in 1995." (PMID 36497436, 2022).
ovarian carcinoma (continued). "BRCA1/2 mutant carriers have a relatively low risk of pancreatic cancer compared to breast and ovarian cancer." (PMID 35163129, 2022). "By analyzing the influence of the vaginal microbiota in women with ovarian cancer or at a high risk of developing this cancer (BRCA1+ mutation or high probability of mutation), an altered and characteristic vaginal microbiome can be found." (PMID 36555661, 2022). "This study assessed the risks associated with BRCA1/2 PVs for 22 first primary cancers, other than female breast and ovarian cancers, and further clarified the cancer spectrum associated with BRCA1/2 PVs." (PMID 35077220, 2022). "Mutations in BRCA1/2 occur in 1 out of 300–500 women, increasing their risk of developing various types of cancer, predominantly breast and ovarian cancer." (PMID 35734436, 2022). "The lifetime risk of developing ovarian and/or fallopian tube cancer (referred to as ovarian cancer hereafter) has been estimated to be between 44 to 49% for women with a BRCA1 mutation and between 17 to 21% for those with a BRCA2 mutation." (PMID 35668475, 2022). "Altogether, in 18 of 158 (11.4%) ovarian cancer patients with BRCA1 or BRCA2 pathogenic mutations were found." (PMID 35382848, 2022). "The nomogram based on the BOADICEA (Breast and Ovarian Analysis of Disease Incidence and Carrier Estimation Algorithm) prediction model can be used to predict breast or ovarian cancer risk in individuals with BRCA1 and BRCA2 mutations." (PMID 36203677, 2022). "The female carriers of BRCA1/2 pathogenic variants (mutations) face a high lifetime risk of developing breast and/or ovarian cancer." (PMID 35356420, 2022). "Till now, numerous studies have demonstrated that mutations of BRCA1/2 increase the lifetime risk of breast or ovarian cancer development." (PMID 36284291, 2022). "In a previous study on selected patients with BC and/or ovarian cancer from the south of Tunisia, the overall frequency of the BRCA1/2 germline mutations was 14.17%, which is lower than ours." (PMID 36672847, 2022). "Women with BRCA1/2 mutations have a higher risk of developing breast and ovarian cancer compared to women of the general population." (PMID 35172875, 2022). "This is an urgent need especially in the subset of patients at high-risk of ovarian cancer due to inherited BRCA1 and BRCA2 mutations." (PMID 36311816, 2022). "BRCA1/2 mutation carriers also benefit from PARP inhibitors, and our previous study demonstrated that fluzoparib, a PARP inhibitor, had antitumor activity in BC and ovarian cancer, particularly in BRCA1/2-mutated patients." (PMID 35494038, 2022). "To uncover the mechanism underlying the apoptotic resistance of BRCA1-deficient ovarian cancer cells, we analyzed the differentially expressed genes (DEGs) between the BRCA1-deficient and -proficient cases." (PMID 35517499, 2022). "BRCA1/2 mutation (BRCAm) are a well-known cause of ovarian cancer and approximately 25% of ovarian cancers exhibit BRCAm." (PMID 35354431, 2022). "This suggests that endogenous cAMP in BRCA1 knock-down ovarian cancer cells can prevent cell death or cell cycle arrest caused by DNA damage." (PMID 35517499, 2022). "Our patient had a synchronous BRCA1 germline mutation which explains the development of HGSC ovarian cancer." (PMID 36531003, 2022). "To date, attention has been focused primarily on women in families with BRCA1/2 mutations, due to the higher impact of those variants in terms of breast and ovarian cancer risk." (PMID 35448177, 2022). "In this study, we moved beyond BRCA1/2 susceptibility testing in breast and ovarian cancer patients to explore the application of pharmacogenetics across multiple genes participating in homologous recombination DNA damage repair." (PMID 36568162, 2022). "PARPi exerted the most notable efficacy in ovarian cancer patients carrying BRCA1/2 mutations, followed by HRD (+) patients." (PMID 35466318, 2022).
ovarian carcinoma (continued). "Germline mutations in BRCA1/2 have been identified in 13–15% of women diagnosed with ovarian cancer, and somatic mutations are found in an additional 7%." (PMID 35681784, 2022). "Germline mutations impairing RAD51C functions are susceptibility factors for breast and ovarian cancers like BRCA1/235." (PMID 36319719, 2022). "Patients harboring germline pathogenic variants (GPVs) in BRCA1/2 have a higher risk of developing breast and/or ovarian cancer." (PMID 35783256, 2022). "In contrast, nearly all women perceived their ovarian cancer risk as more threatening, or as Louise (56 years, BRCA1) described, “a time bomb just waiting to go off”." (PMID 35887609, 2022). "In a study of BRCA1-deficient ovarian cancer, dendritic cells expressed upregulated levels of CD80, CD86, and MHC II expression after olaparib treatment in comparison to the study’s vehicle control and the PD-1 antibody." (PMID 36071479, 2022). "For instance, women with a BRCA1/2 pathogenic mutation are at a much greater risk of developing breast and ovarian cancer than those in the general population." (PMID 36013212, 2022). "Levels of willingness to undergo BRCA1/2 testing and preventive measures for breast and ovarian cancer risk, however, provide some useful indicators of public awareness regarding testing and the potential demand for information about testing." (PMID 35629239, 2022). "Despite the significant genetic component to this disease, studies estimate that fewer than 14% of BRCA1/2 PV carriers are identified, with lower rates for PV carriers in the other genes linked to ovarian cancer risk." (PMID 36883408, 2022). "In a cohort of 8,162 breast/ovarian cancer families from the German Consortium for Hereditary Breast and Ovarian Cancer, eight female DH patients for BRCA1 and BRCA2 mutations were described and analyzed for their phenotypic features." (PMID 36003761, 2022). "Although PARPi were initially studied and approved in BRCA1/2 mutated ovarian cancers, its use has been expanded to other cancers, including breast cancer, pancreatic cancer, and prostate cancer." (PMID 35626165, 2022). "Restoration of BRCA1 function through the loss of BRCA1 promoter methylation has been demonstrated to confer resistance to PARP inhibitors in ovarian carcinoma." (PMID 36551731, 2022). "In this study, we performed the NGS study of BRCA1/2 genes in the same group of 158 women affected with ovarian cancer and diagnosed 18 (11.4%) BRCA1/2 mutation carriers." (PMID 35382848, 2022). "Carriers of (likely) pathogenic germline variants of BRCA1, which is the focus of this study, have a lifetime risk of 56–75% for breast cancer and 36–51% for ovarian cancer." (PMID 34981296, 2022). "PV’s in at least 11 different genes, including BRCA1 and BRCA2 (BRCA1/2), confer an increased risk for ovarian cancer." (PMID 36883408, 2022). "Overexpression of miR-622 is implicated in the development of resistance to PARPIs and cisplatin by restoring HR and impairing NHEJ in BRCA1-deficient ovarian cancer." (PMID 35785170, 2022). "This very recent milestone of biomarker-guided, first-line PARPi treatment has been based on the knowledge that ovarian cancer with BRCA1/2 mutations comprises a molecular Achilles’ Heel that can be exploited by targeting HRD." (PMID 36338759, 2022). "There were two cases of ovarian cancer in a patient with Li-Fraumeni syndrome and in a BRCA1 mutation carrier, respectively." (PMID 35892866, 2022). "Most breast and ovarian cancers are sporadic, however, a germline pathogenic mutation in BRCA1 or BRCA2 genes is carried in approximately 5% of BC and 10–15% of EOC patients." (PMID 36307994, 2022).
ovarian carcinoma (continued). "Poly(ADP-ribose) polymerases inhibitor (PARPi) have shown clinical efficacy in ovarian carcinoma, especially in those harboring defects in homologous recombination (HR) repair, including BRCA1 and BRCA2 mutated tumors." (PMID 35406579, 2022). "Women who carry an inherited pathogenic BRCA1 mutation present an increased risk of developing breast and ovarian cancer." (PMID 35619904, 2022). "While lifetime risk of developing ovarian cancer for women in the general population is about 1.2%, the risk was estimated to be 39–59% and 11–17% for women who carry BRCA1 and BRCA2 mutations, respectively, by age 70–80." (PMID 35625955, 2022). "Overall, this is the first study that evaluates the readthrough of PTC variants with clinical relevance in the breast and ovarian cancer-predisposing gene BRCA1." (PMID 35837282, 2022). "For example, hereditary mutations of the BRCA1/BRCA2 genes in breast or ovarian cancer disable high-fidelity HRR of harmful DSBs." (PMID 36253861, 2022). "Although women with BRCA1 mutation have an increased risk of developing ovarian cancer, the rate of BRCA1 mutation in ovarian cancer patients is only 10%–16%." (PMID 36703740, 2022). "PARP inhibitors improved progression-free survival in recurrent ovarian cancer patients with BRCA1/2 mutation and platinum-sensitive by 13.6 months." (PMID 36035179, 2022). "FANCD2 is significantly overexpressed in BRCA1/2-mutated breast or ovarian cancers, highlighting its importance in limiting replication stress." (PMID 35681784, 2022). "In the context of genetic testing in a woman with breast or ovarian cancer in which a mosaic BRCA1/BRCA2 pathogenic variant is found, it currently remains appropriate to discuss risk management options as for constitutional carriers." (PMID 36068545, 2022). "Pathogenic germline variants in BRCA1 gene have been associated with familial risk of breast and ovarian cancers (OMIM: 604370)." (PMID 35280729, 2022). "Although PARPi have greatly improved the outcomes of patients with ovarian cancer, especially among patients harboring BRCA1/2 mutations, the development of drug resistance remains a vexing challenge in most patients." (PMID 35332131, 2022). "The combination of olaparib and tremelimumab was verified in a phase I/II study [NCT02571725]14 involving women with BRCA1/2-deficient recurrent ovarian cancer." (PMID 36533080, 2022). "Lifetime risk of developing BC is as high as 80% in BRCA1 gene along with development of ovarian cancer." (PMID 36268285, 2022). "Poly-ADP ribose polymerase (PARP) inhibitors target HRD to induce synthetic lethality and are used routinely in the treatment of BRCA1 mutated ovarian cancer in the platinum-sensitive maintenance setting." (PMID 35990583, 2022). "Herein, we show that the ability of cisplatin or taxol to induce senescence in ovarian cancer cells depends on tumor genotype, being substantially more pronounced following treatment of Brca1-deficient (compared to Brca1-proficient) ovarian tumors." (PMID 35082152, 2022). "In a retrospective cohort of 5799 families (men/women) from the HBOC group, an increased risk of PC was observed in breast and ovarian cancer patients both carrying BRCA1 and BRCA2 gene mutations." (PMID 35761384, 2022). "BRCA1 is an important tumor suppressor, and 35.3% of BRCA1 dysfunction in ovarian cancer was found to be unrelated to germline or somatic mutations." (PMID 36175480, 2022). "The most frequent SFs gene was BRCA2 (16 variants in 19 individuals), followed by BRCA1 (9 variants in 9 individuals), both of which were associated with increased susceptibility to breast and ovarian cancer." (PMID 36143288, 2022). "Patients with breast or ovarian cancer family history were more likely to carry BRCA1/2 mutations, and ones with DDR mutations had worse survival." (PMID 35494038, 2022).
ovarian carcinoma (continued). "In ovarian cancer, BRCA1 mutation is constitutively associated with the activation of the NF-κB p65 subunit, and in OC treated with inhibitors of DNA damage repair, with activation of NF-κB p50 subunit, respectively." (PMID 35269636, 2022). "The cumulative risk of breast cancer development by the age of 80 years for BRCA1 pathogenic variant carriers is estimated at 72% and of ovarian cancer at 44% and for BRCA2 at 69% and 17%, respectively." (PMID 36171877, 2022). "Given the fact that most ovarian cancer patients undergo either a more targeted genetic testing e.g. BRCA1/2 gene test or an only somatic mutation test, this genome-wide analysis is of high value." (PMID 36531003, 2022). "As expected, BRCA1/2 had both germline and somatic pathogenic variation in breast and ovarian cancer, whereas BRCAness genes had high prevalence of somatic pathogenic variation distributed in cancer type-specific manners." (PMID 36497135, 2022). "Approximately 11–15% of all epithelial ovarian cancer (EOC) patients carry a BRCA1 or BRCA2 germline pathogenic variant (gPV)." (PMID 36137114, 2022). "For ovarian cancer patients, germline and somatic BRCA1/2 mutations have been utilized as biomarkers for the use of PAPRi." (PMID 36147908, 2022). "The pathogenic variant (PV) or likely pathogenic variant (LPV) BRCA1/2 gene is strongly associated with hereditary breast or ovarian cancer." (PMID 35115620, 2022). "Germline mutations in BRCA1/2 are associated with a high risk of cancers, particularly breast and ovarian cancers." (PMID 36147908, 2022). "Currently, tumour sample testing for ovarian cancer involves testing for BRCA1/2 mutations and HR deficiency status, which predicts the response to platinum agents and PARP inhibitors." (PMID 35805770, 2022). "The breast and ovarian cancer susceptibility gene (BRCA1) is a tumor suppressor whose mutation has been associated with the development of breast, ovarian and, probably, other malignancies at young ages." (PMID 35432218, 2022). "One of those patients was a female carrier of BRCA1 KP variants (familial breast/ovarian cancer, MIM 604370), whose mother and maternal grandmother were diagnosed with benign breast nodules." (PMID 36143288, 2022). "We evaluated matched primary and recurrent ovarian cancer from 14 women, 10 BRCA1 and four BRCA2 pathogenic variant carriers." (PMID 36344544, 2022). "Although BRCA1 mutant and promoter methylated ovarian cancer cells are synthetically lethal with PARPI, the loss of the target (PARP) results in PARPI resistance." (PMID 35785170, 2022). "The reported germline I482* variant in BRCA1 gene was associated with familial ovarian cancer predisposition in German and Japanese populations." (PMID 35753294, 2022). "Several phase-3 randomized controlled trials demonstrated improved PFS and OS using different PARPi in BRCA1/2 mutated breast and ovarian cancers." (PMID 36358724, 2022). "As therapy on BRCA variants is deeply explored in breast and ovarian cancer, this result replicates the importance of BRCA1/2 detection for ESCC treatment." (PMID 36272974, 2022). "To explore the effects of BRCA1 deficiency in the ovarian cancer patients, we analyzed mRNA expression differences between the BRCA1-deficient and -proficient groups using Gene set enrichment analysis (GSEA)." (PMID 35517499, 2022). "BRCA1 mutations are also associated with increased risks of other cancers; for example, pancreatic cancer, prostate cancer, and ovarian cancer." (PMID 36010323, 2022). "BRCA1/2 mutations are found in most hereditary ovarian cancers with about 15% of women with high grade serous ovarian cancer (HGSOC) having a germline BRCA mutation and 5% having somatic BRCA mutations." (PMID 35736348, 2022).